BRCA1 (BRCA1 DNA repair associated)
Diseases named in the same sentence as BRCA1 in open-access papers (continued):
Sharing a sentence is not in itself a finding about the gene and the disease.
breast cancer (continued). "Thus BRCA1 mutation associated breast cancers are generally poorly differentiated and more frequently display typical and atypical medullary-like morphology than sporadic tumours." (PMID 19724277, 2009). "Despite these differences in familial phenotype, the majority of families present only early onset breast cancer and there is little to indicate which gene should be targeted first for more efficient mutation screening or if in fact one of the BRCA1 or BRCA2 gene is at cause." (PMID 19352458, 2009). "In the study presented here, we set out to determine whether increased EZH2 expression also characterizes human BRCA1-deficient breast cancer, and whether BRCA1-deficient tumor cells are dependent on high EZH2 levels for their survival." (PMID 19709408, 2009). "Also, we compared survival in BRCA1 mutation carriers with a control group with sporadic breast cancer matched for age, stage and time of diagnosis." (PMID 19366445, 2009). "We have screened 987 samples from unselected breast cancer patients for the four most common BRCA1 mutations in Greece: c.5266dupC (5382insC), G1738R (c.5212G>A), the 3.2 kb deletion of exon 20 (c.5256_5277+3179del3200), and the 4.4 kb deletion of exon 24 (c.5468-285_5592+4019del4429_insCACAG)." (PMID 19491894, 2009). "Importantly, our mouse model allows us to compare BRCA1-deficient mammary tumors (arising in K14cre;Brca1F/F;p53F/F (KB1P) mice) with BRCA1-proficient control tumors (arising in K14cre;Brca1w." (PMID 19709408, 2009). "We indeed found that BRCA1-deficient mouse mammary tumors have higher EZH2 protein levels than control tumors, also indicated by the higher percentage of tumor cells with EZH2 expression above background (77% in KB1P tumors versus 11.5% in KP tumors; Wilcoxon P < 0.029)." (PMID 19709408, 2009). "Although this increase is not statistically significant (data not shown), it is in agreement with previous analyses that describe genomic gains/amplifications at 13q34 in ER-negative tumors, basal-like tumors, BRCA1-associated breast cancers, and medullary carcinomas." (PMID 19995430, 2009). "However, BRCA1/2 mutations account for only a small subgroup of women with a family history of breast cancer." (PMID 18834503, 2008). "Given that hereditary breast carcinoma is primarily due to germline mutations in one of two breast cancer susceptibility genes, BRCA1 and BRCA2, we have characterised the spectrum of BRCA mutations in a cohort of 37 individuals with early-onset disease (≤40 years) and no reported family history." (PMID 18431501, 2008). "This may be why tamoxifen has proven to be effective in preventing the development of contralateral breast cancer in BRCA1 mutation carriers." (PMID 18405391, 2008). "Development of multiple mouse models with deletion or mutations in Brca1 targeted to the mammary gland has provided an opportunity to examine the biology and therapeutic implications of BRCA1 loss in breast cancer and some studies find similarities between the mouse and human tumors." (PMID 18394172, 2008). "Thus, individual Brca1-deficient mouse mammary tumors gave rise to cell lines with distinct populations of cells expressing stem cell markers." (PMID 18241344, 2008). "The breast cancer susceptibility protein, BRCA1 functions to maintain the integrity of the genome." (PMID 18545657, 2008). "In spite of previously established genomic instability associated with Brca1 deficiency, transplantation of original Brca1 mouse mammary tumors into naïve recipients and generation of cell lines from these tumors provides a reliable source of material with relatively stable expression profile." (PMID 18394172, 2008). "Because BRCA1's function is implicated in the chemosensitivity of cells to DNA damage-inducing reagents, elucidating the mechanisms of the BRCA1 pathways is now a critical issue directly linked to the clinical breast cancer field." (PMID 18179693, 2008).
breast cancer (continued). "This indication has been derived from estimates based on data from cancer-prone families or from BRCA1/2 mutation families, and might be biased because BRCA1/2 mutations explain only a small proportion of the familial clustering of breast cancer." (PMID 18651949, 2008). "This is absolutely true for the treatment of breast cancer caused by BRCA1 gene mutations." (PMID 19007432, 2008). "Up to 5% breast cancer cases are attributable to inherited mutations in the BRCA1 or BRCA2 genes." (PMID 18394172, 2008). "BRCA1 has been implicated in numerous DNA repair pathways that maintain genome integrity, however the function responsible for its tumor suppressor activity in breast cancer remains obscure." (PMID 18197258, 2008). "We hypothesised that inactivation of BRCA1 by promoter methylation could occur as a germline or an early somatic event that predisposes to breast cancer with the phenotype normally associated with BRCA1 germline mutation." (PMID 18269736, 2008). "This appears to have been mentioned only once in a letter to the Editor of the Journal of Clinical Oncology which reported on estrogen receptor-beta expression in hereditary breast cancer where positive staining for ERβ was detectable in 94% (15 of 16) of BRCA1 associated breast cancers." (PMID 18405391, 2008). "We hypothesised that some individuals are predisposed to develop breast cancer with the features associated with BRCA1 mutations because they carry a methylated BRCA1 allele in their somatic tissues." (PMID 18269736, 2008). "Prevalence of BRCA1 mutations in our study was 6.25% (4/64) among familial breast cancer patients." (PMID 18662409, 2008). "The continuing uncertainty as to the exact penetrance for breast cancer among BRCA1 mutation carriers may be due to several factors including differences owing to study design, allelic heterogeneity and to modifying genetic and or environmental factors." (PMID 18759965, 2008). "Mutation of the central BRCA1 gene results in ~80% penetrance of breast cancer, and BRCA1 gene methylation or the accumulated dysfunctions of other proteins whose single mutation causes low penetrance are thought to result in sporadic breast cancer." (PMID 19007432, 2008). "Understanding how estrogen regulates BRCA1 expression may contribute to clarifying the role played BRCA1 under normal physiological conditions and pathophysiological perturbations that predispose to breast cancer." (PMID 18377656, 2008). "Pushing margins have been found in BRCA1 mutation-positive patients with breast cancer." (PMID 18283315, 2008). "We found that the best predictive factors for the presence of a BRCA1 or BRCA2 mutation are families with at least two cases of breast cancer, at least one of which occuring before the age of 50 (p = 0.0335), and families with a history of both breast and ovarian cancer (p < 0.0001)." (PMID 18627636, 2008). "We studied the effect of these polymorphisms on breast cancer (BC) risk in BRCA1/2 carriers." (PMID 18542066, 2008). "According to this model, genetic susceptibility to breast cancer is explained by the effects of BRCA1 and BRCA2 mutations, and the residual familial clustering is explained by the joint multiplicative effect of a large number of genes each of small effect (i.e., by a polygenic component)." (PMID 18349832, 2008). "In order to identify a key pathway that may underlie the tumorigenic potential of BRCA1 in breast cancer, we took advantage of the evolutionary distance between humans and yeast." (PMID 18197258, 2008).
breast cancer (continued). "Consequently, a breast cancer only phenotype was found in a minority of BRCA1 mutation families (14 out of 38), but a majority of BRCA2 families (11 out of 18)." (PMID 18783588, 2008). "Thus, breast cancer risks in large familial breast cancer kindreds with BRCA1/BRCA2 mutations are substantially higher than risks derived from population based studies." (PMID 18513387, 2008). "As BRCA1/2 mutations explain only a small proportion of the familial clustering of breast cancer, estimates based on these high-risk families may thus have limited value for the prediction of the age of onset of breast cancer in the general population." (PMID 18651949, 2008). "However, the Brca1 deficient mouse mammary tumors have variable penetrance and latency, which makes it nearly impossible to use these models to standardize therapies and to study the stem cell population." (PMID 18241344, 2008). "Of the 106 BC samples a subset of 29 group-A and 33 group-B breast samples were further studied to find out the association between the candidate genes with some breast cancer susceptibility genes like BRCA1, BRCA2 that are intermittently associated with breast cancer." (PMID 18990233, 2008). "This may explain the effectiveness of tamoxifen in preventing contralateral breast cancer development in BRCA1 mutation carriers." (PMID 18405391, 2008). "However, lower estimates of lifetime risk for breast cancer of 66% in BRCA1 carriers and 45% in BRCA2 carriers were reported in subsequent population-based studies of pooled data." (PMID 18402691, 2008). "Loss of BRCA1 function has been found in basal-like breast cancer." (PMID 18950515, 2008). "Interestingly, due to the characteristic defects in DNA repair seen in BRCA1 mutation-associated tumours, sensitivities to standard cytotoxic agents differ compared with other breast cancers." (PMID 18182985, 2008). "Finding new immunohistochemical markers that are specific to hereditary breast cancer could help us to select candidates for BRCA1/BRCA2 mutation testing and to understand the biological pathways of tumour development." (PMID 18275599, 2008). "In addition, mouse model using Brca1 deficiency has suggested an important role for BRCA1 in basal-like breast carcinoma with metaplastic elements." (PMID 18559079, 2008). "Significantly, breast cancer associated BRCT domain defects in BRCA1 that suppressed P-CTD cleavage and lethality in yeast also suppressed the physical interaction of BRCA1 with human SPT5 in breast epithelial cells, thus confirming SPT5 as a relevant target of BRCA1 interaction." (PMID 18197258, 2008). "Recently we showed that diagnostic ionising radiation exposure from chest X-rays may be associated with a significantly increased breast cancer risk among women who carry BRCA1 or BRCA2 pathogenic germline mutations." (PMID 17428320, 2007). "However, BCoR-L1 expression was found to be decreased in a variety of breast cancer subjects, including BRCA1/2 mutation carriers and 'sporadic' breast cancer subjects." (PMID 17697391, 2007). "Similarly expression of BRCA-1, an infamous breast cancer gene, is associated with embryonic cellular proliferation and with differentiation of ectodermally- and mesodermally- derived tissues in the mouse." (PMID 18030336, 2007). "The aim of the present study was to attempt to elucidate a role for BCoR-L1 as a high-risk breast cancer predisposition gene by mutation screening of well-characterised non-BRCA1/2 familial breast cancer subjects who were selected to maximise the probability of identifying a mutation." (PMID 17697391, 2007). "However, in some studies, OC use has been found to increase breast cancer risk among women with known BRCA1 or BRCA2 germline variants." (PMID 17553133, 2007).
breast cancer (continued). "In some sporadic breast cancers, the poor outcome associated with BRCA1 methylation and low levels of expression could be explained by MYC amplification." (PMID 17987116, 2007). "Overall, there is an emerging picture indicating that breast cancer risk in BRCA1 and BRCA2 positive women are substantially higher than in the general population and the genes are considerably affected by non-genetic, environmental factors and by additional genetic modifiers." (PMID 18053234, 2007). "Thus, an impaired cellular response to DNA damage appears to be a plausible mechanism whereby BRCA1 mutation carriers are at an increased risk of breast cancer." (PMID 17213827, 2007). "Moreover, it has also been shown that MYC contributes to tumor progression in BRCA1-associated breast cancers and that it was gained or amplified in 53% of cases." (PMID 17417968, 2007). "Breast cancer arising due to a high penetrance genetic predisposition gene such as BRCA1 or BRCA2 occurs at younger average age than breast cancer in the general population and a higher proportion of young onset cases will have a genetic predisposition than breast cancer cases in general." (PMID 17697367, 2007). "Second corpus cancer has been observed to be in excess after primary sporadic and familial breast cancers; BRCA1, BRCA2, and E-cadherin gene may be shared genetic risk factors for the two cancer sites." (PMID 17406355, 2007). "However, low-dose ionising radiation has recently been shown to increase the risk of breast cancer significantly among BRCA1 and BRCA2 mutation carriers." (PMID 17428320, 2007). "Additionally, associations with OCs have been noted among some subsets of breast cancer cases, including younger women, those with a family history of breast cancer, germline mutations in BRCA1 or BRCA2, or other genetic polymorphisms." (PMID 17553133, 2007). "The breast cancer susceptibility gene, BRCA1, is involved in the development of a significant proportion of familial breast and ovarian cancers and may also play a role in the development of sporadic breast cancer." (PMID 17511879, 2007). "Methylation analysis of free DNA in DL fluid may offer a useful surrogate marker for BRCA1/2 mutation status and/or breast cancer risk." (PMID 17324252, 2007). "It has been found that BRCA1-mutated breast carcinomas are almost always triple negative; it would be interesting to know whether BRCA1 mutated tumors have a distinct gene-expression profile that distinguished them from the other basal type tumors." (PMID 17910759, 2007). "However, there is also experimental evidence that ionising radiation induces various molecular changes in breast epithelial cells and that a BRCA1-mutated breast cancer cell line shows deficient repair and increased chromosomal aberration." (PMID 16404418, 2006). "It is important to determine what these effects may be because of the increasing use of endocrine agents such as TAM for breast cancer prevention in BRCA1 and BRCA2 mutation carriers." (PMID 16538216, 2006). "When information on family members was restricted to the second-degree relatives of the first screened individual, the under-prediction of BRCA1 mutations was mainly among families with at least three cases of breast cancer and at least one case of ovarian cancer (3.12 expected versus 6 observed)." (PMID 16417652, 2006). "There is considerable interest in whether anti-oestrogens can be used to prevent breast cancer in women bearing mutations in the BRCA1 and BRCA2 genes." (PMID 16538216, 2006). "Our results suggest that parity may have a similar effect on breast cancer risk among BRCA1 and BRCA2 mutation carriers." (PMID 17187672, 2006). "However, two or more births conferred significantly lower breast cancer risk only among BRCA1 mutation carriers." (PMID 17187672, 2006). "The effects of heterozygous mutations in the BRCA1 or BRCA2 breast cancer-predisposing genes on the endocrine sensitivity of human breast epithelial cells are unknown." (PMID 16538216, 2006).
breast cancer (continued). "Genetic analysis of the subjects who developed breast cancer in the NSABP P-1 Breast Cancer Prevention Trial indicates that the Gail model inefficiently identifies BRCA1 and BRCA2 mutation carriers, since only 6.6% (19/288) of that high-risk population carried such mutations." (PMID 16800895, 2006). "Higher frequencies, 5.1–11.4%, of the CHEK2 1100delC allele have by some investigators been reported in non-BRCA1/2 families with hereditary breast cancer, although other studies from e.g. Australia and Spain have not found an increased frequency in such families." (PMID 16539695, 2006). "There has been a dearth of evidence-based screening guidelines for women age < 40 with a family history of breast cancer, a BRCA1 or BRCA2 mutation, or other risk factors, largely because of the lack of randomized, controlled trials to inform the development of such guidelines." (PMID 16800895, 2006). "This supports the observation that SNPs of XPD (ERCC2), BARD1 and IL-10 may be good candidates for breast cancer predisposition, which may also modify the effect of BRCA1 in carriers." (PMID 16672066, 2006). "A high calculated risk from the Tyrer-Cuzick algorithms correlated closely with the subsequent occurrence of breast cancer in BRCA1 and BRCA2 mutation positive families, but this was less evident in families in which no pathogenic BRCA1 or BRCA2 mutation has been detected." (PMID 16507150, 2006). "The results suggest that the relative risks of breast cancer associated with parity among BRCA1 and BRCA2 mutation carriers may be similar to those in the general population and that reproductive history may be used to improve risk prediction in carriers." (PMID 17187672, 2006). "BACH1 (BRCA1-associated C-terminal helicase 1, also known as BRCA1-interacting protein 1, BRIP1; GenBank: NM_032043) belongs to a DEAH helicase family and interacts in vivo with BRCA1, the protein product of one of the two major genes for hereditary breast cancer susceptibility." (PMID 16430786, 2006). "BRCA1 or BRCA2 germline mutations increase the risk of developing breast cancer." (PMID 16846527, 2006). "This difference might suggest differences in the development of breast cancer among BRCA1 and BRCA2 mutation carriers." (PMID 17187672, 2006). "In this latter report they found evidence of increasing risk with increasing parity among BRCA2 mutation carriers and that BRCA1 mutation carriers with four of more children were at a significantly lower risk of developing breast cancer than nulliparous carriers." (PMID 17187672, 2006). "The BRCA1 gene is implicated in both familial and sporadic breast cancers." (PMID 16280041, 2005). "We asked whether there is an association between changes in body weight and the risk of breast cancer in women who carry a mutation in either breast cancer susceptibility gene, BRCA1 or BRCA2." (PMID 16168130, 2005). "We performed a matched case–control study to investigate whether or not there is an association between changes in body weight and the risk of breast cancer in women with a deleterious BRCA1 or BRCA2 mutation." (PMID 16168130, 2005). "We conducted our study to examine whether change in body weight modifies the risk of breast cancer among women who carry a deleterious BRCA1 or BRCA2 mutation." (PMID 16168130, 2005). "Thus, the frequency of EGFR mutations was significantly higher in BRCA1/2-related breast cancers compared to that in sporadic ones (P=0.0079)." (PMID 15841079, 2005). "If similar rates of breast cancer development are observed in the UK and US centres, it is probable that these samples can be used to identify cytological, biological and molecular biomarkers for breast cancer risk in women with germline BRCA1/2 mutations." (PMID 16457692, 2005).